CD4 (CD4 molecule)
Diseases named in the same sentence as CD4 in open-access papers (continued):
Sharing a sentence is not in itself a finding about the gene and the disease.
tumor (continued). "Consequently, increased levels of extracellular collagen deposition were associated with a reduction of CD8+ T cells, CD4+ T cells, macrophages, and NK cells tumour infiltration in MLiM." (PMID 39496484, 2024). "Comparing IL-4 expression in thymocyte selection-associated HMG BOX (TOX)+ CD4+ T-cells between plaque and tumor lesions, a significant increase in IL-4 and TOX expression was observed in the tumor stage, with a positive correlation between the levels of TOX and IL-4 expression." (PMID 38397043, 2024). "In this context, the association between immune dysregulation and higher IgM levels linked to persistent inflammation, a reduced CD4 T cell compartment, and the use of immunosuppressive therapies to manage these complications, synergistically contributes to the development of neoplasia." (PMID 39478863, 2024). "However, the use of RITs to deplete Tregs has strong side effects, as this therapy also affects CD4+ CD25hi effector T cells, further weakening the body’s anti-tumor immunity and increasing the patient’s risk of developing autoimmune diseases." (PMID 39227959, 2024). "Interestingly, while tumor tissue TCF1+ CD4 T cells were associated with a favorable response, as previously reported, a high abundance of these cells (and TCF1+ CD8+ T cells) circulating in the bloodstream prior to treatment was unfavorable." (PMID 39190534, 2024). "Furthermore, anti-CD4 treatment caused tumor recurrence after immunotherapy in EMT6-injected mice, but produced no apparent effect in either EMT6 or 4THM tumor bearers after chemotherapy treatment." (PMID 38540350, 2024). "Immune marker analyses of Ing4-deleted tumors revealed a significant increase in tumor-associated macrophages (Gr-1loCD11b+F4/80+) and a decrease in granzyme B-positive (GzmB+) CD4+ T cells, indicating a suppressive and/or less tumoricidal immune microenvironment." (PMID 38968186, 2024). "In addition, Cytokines like IL-2, IL-12, IL-23, and TNF-α can be produced by tumor-associated macrophages, dendritic cells, or CD4+ T cells, all of which are paired with CTL, NK cells, Th17 cells proliferation." (PMID 38887597, 2024). "HSD17B6 exhibited a strong association with tumor-infiltrating B cells, CD4+ and CD8+ T cells, neutrophils, dendritic cells, and macrophages.It has been proposed by earlier research that HSD17B6 may prevent tumor growth." (PMID 38725005, 2024). "We thus reason that apCAFs may potentially be associated with anti-tumor immune effects by promoting the survival of CD4+ effector T cells through the reported mechanism of expressing C1Q molecules." (PMID 38903527, 2024). "VEGF creates a pro-tumor environment by inhibiting the activation of cytotoxic T lymphocytes (CTLs) and increasing the number and function of suppressive regulatory lymphocytes (Tregs), tumor-associated macrophages (TAMs) and the number of T cells CD4+ memory." (PMID 38397167, 2024). "CD4+ T cells within the tumor showed signs of glucose deficiency and MR of CD4+ T cells to increase PEP production may enhance T cell-mediated antitumor immune responses." (PMID 39588377, 2024). "Together, our findings indicate that specific-activated Treg subsets are expanded in patients with advanced disease and increase in the frequency of this subset among CD4+ T cells is associated with the TTM indicator of the tumour mass within all major body compartments in patients before therapy." (PMID 39335199, 2024). "Consequently, CD8+/CD4+ T-cell infiltration was significantly enhanced and neutralized the tumor-promoting effect mediated by Wdr5 deficiency-induced MHC I downregulation." (PMID 39201460, 2024). "Additionally, these co-expressed CD4+ T cells recognize both tumor-associated antigens and tumor-specific neoantigens, thereby contributing to tumor immunity." (PMID 38426090, 2024).
tumor (continued). "Nonetheless, tumor-associated antigen responses were linked to distinct patterns of T cell infiltration, with higher antibody levels observed in patients with greater densities of CD4+ T cells." (PMID 39136024, 2024). "We further developed the immune infiltrations analysis, which demonstrated that glycosylation was positively associated with B cells (naive) and CD4+ T cells (memory resting) and negatively related to T cells (follicular helper), that play crucial roles in tumor immune microenvironment." (PMID 38562924, 2024). "Immune cells with anti-tumor effects typically include M1 macrophages, cytotoxic CD8+ T lymphocytes, natural killer (NK) cells, and neutrophils, while M2 macrophages, Forkhead box protein P3 (FOXP3)+ T cells, and CD4+ helper T cells are often associated with promoting tumor growth." (PMID 38716256, 2024). "HLA-DR positive cells in particular seem to be crucial for immunological tumor control, as HLA-DR loss is linked to tumor escape from immunosurveillance, and higher numbers of activated HLA-DR + CD4 + cells were associated with a better prognosis in B-NHL patients." (PMID 38987735, 2024). "Another biomarker that may predict response to ICIs in breast cancer is the presence of tumor infiltrating lymphocytes (TILs), such as CD4+ T cells, CD8+ T cells, NK cells, and Th1, which cause an anti-tumor effect through IFN-γ signaling." (PMID 39722028, 2024). "In addition, in adoptive cell therapy for lung cancer (LC), miR-7 deficiency in CD4+ T cells enhances Th1 polarization and activation, markedly reducing tumor growth and boosting CD8+ T cell responses." (PMID 39438986, 2024). "Inflamed ovarian tumors with intra-epithelial compartment T-cells have been shown to have a favourable outcome, and it was recently shown that for BRCA1/2 mutated HGSCs, increased proximity of CD8+ and CD4 + T-cells to Ki67+ tumor cells was associated to improved prognosis." (PMID 39026018, 2024). "MR of tumor microenvironment: A 2012 study in Cell showed that there may be metabolic competition between T cells and tumor cells, CD4+ T cells within the tumor showed signs of glucose deficiency and diminished anti-tumor effector function." (PMID 39588377, 2024). "To enhance the understanding of the relationship between CLEC11A and TILs, we explored the association between CLEC11A and different biomarkers of TILs (CD8+/CD4+ T cells, B cells, monocytes, tumor-associated macrophages [TAMs], M1/M2 macrophages, neutrophils, NK cells, T cells, and DCs)." (PMID 37597212, 2024). "Additional studies investigating driver mutations in canine CD4+ PTCL may help identify mechanisms contributing to the contradictory immature tumor cell transcriptome with surface expression of mature T-cell markers." (PMID 38166662, 2024). "The elevated presence of resting NK cells and activated CD4+ memory T cells in high‐risk cases might indicate a state of immune evasion or adaptation by the tumour cells." (PMID 38973477, 2024). "All M6LSig genes were significantly correlated with at least one immune cell type abundance in the tumor microenvironment, and the risk score was positively correlated with CD4+ naïve T cell abundance and negatively correlated with follicular helper T cells and eosinophils." (PMID 39198884, 2024). "Intriguingly, this conclusion aligned with our findings from the EPIC analysis and CIBERSORT, strongly suggesting that the MPIGs-derived risk scores can distinguish between two tumor immune microenvironments characterized by different cell types, including CD4+ T cells, B cells, and macrophages." (PMID 38696324, 2024). "Furthermore, tumours with higher infiltration levels of PD-L1+ lymphocytes in tumour islets were significantly associated with higher Foxp3+CD4+ T cell infiltration, despite the distribution of these cells." (PMID 39409156, 2024).
tumor (continued). "Some genotoxins from pathogenic bacteria can also induce CD4+ T-cell senescence through DNA damage, suggesting that the gastrointestinal microbiota may complicate the tumor immunosenescence microenvironment." (PMID 39007138, 2024). "We hypothesize that most CD4 T cells associated with K17-positive tumor areas are Tregs and that K17 contributes to PDAC growth by suppressing T cell infiltration." (PMID 38730319, 2024). "The density of CD8 + T cells in the tumor area was significantly associated with the percentage of radiographic response (P = 0.0005), and so were the densities of M1-like macrophage cells (P = 0.009) and CD4 + T cells (P = 0.021), respectively." (PMID 38467604, 2024). "Several reports demonstrated that alterations in the composition of gut microbiota and their translocation to secondary lymphoid organs can stimulate immune responses against tumors by influencing various cell types such as CD8+ and CD4+ T cells as well as tumor-associated myeloid cells." (PMID 38444857, 2024). "Finally, a high density of FoxP3− CD4+ helper T cells in the tumor margin was independently associated with favorable progression-free survival (PFS) and overall survival (OS)." (PMID 39683528, 2024). "The different immune cells mentioned in this review, such as Tumor-Associated Macrophages (TAMs), CD4+ T cells, Dendritic Cells (DCs), Regulatory T cells (Tregs), and Tumor-Associated Neutrophils (TANs), each play specific roles and mechanisms in the metastasis of CRC." (PMID 38415252, 2024). "The proportion of DCs was larger in the immuno-group compared to the chemo-group, which may be explained by the fact that immunotherapy caused the tumor’s immune system to become more active, and that more DCs were needed to cause a CD4 T cell response." (PMID 39256364, 2024). "Interestingly, mice depleted of CD4+ T cells also demonstrated earlier resistance development to BRAFi therapy indicating an essential contribution of CD4+ T cells to tumor regression caused by BRAFi treatment." (PMID 38631706, 2024). "Moreover, the reversal of the CD8/CD4 ratio in patients with CC was strongly associated with accelerated tumor growth and lymph node metastasis, which suggested a promoting tumor role of CD4 in the TME of CC." (PMID 38672263, 2024). "Moreover, in tumors treated with PHA-793887, there was a significant increase in the infiltration of CD8+ T cells and effector CD4+ T cells, along with a decrease in tumor-associated macrophages (TAMs) and regulatory T cells (Tregs)." (PMID 39676867, 2024). "Our results may suggest that IL17A+CD4+ T cells associated with PD-L1+ lymphocytes can lead to immunosuppression and a tumour-immune escape acting in tumour islets." (PMID 39409156, 2024). "Furthermore, we observed that pretreatment tumor tissues from female patients had markedly lower tumor mutation and neoantigen burden, but significantly higher CD4, CD4/FOXP3, and CD4/FOXP3/PD‐L1 expression level than male patients." (PMID 38899854, 2024). "We speculated that higher immunosenescence levels are associated with more tumor-infiltrating CD4 naive T cells and more differentiation of iTreg and Tfh cells." (PMID 39796714, 2024). "Moreover, soluble GITR ligand (GITRL), when used at a low concentration of 10 μg/mL, has been associated with a significant reduction of tumor-derived Tregs proliferation and of effector CD4+ T cells cytokine production." (PMID 39061246, 2024). "Nonetheless, the mere ability of B cells to present antigens to CD4+ T cells in tumor-associated tertiary lymphoid organs might be hindered due to a lower level of infiltration in INHBA-enriched OPSCC tumors." (PMID 38329386, 2024). "The analysis revealed that a higher infiltration of CD4+ T lymphocytes in the tumor was associated with a shorter PCa specific-free survival in both univariate (HR= 2.03, 95% CI=1.15–3.59, p=0.015) and multivariate (HR=2.29, 95% CI=1.25-4.22, p=0.008) analyses." (PMID 38887294, 2024).
tumor (continued). "The results showed that in all algorithms and cohorts, the low-risk group had higher numbers of plasma cells, NK cells, and certain CD4+ T cells (such as activated memory CD4+ T cells, Th1 cells, and Th2 cells), while tumor-associated fibroblasts (CAFs) showed the opposite trend." (PMID 38499384, 2024). "Studies have confirmed that activated memory CD4 T cells could secret interleukin 17, which promotes tumor progression and is associated with inferior survival outcomes." (PMID 39060620, 2024). "The main infiltrating immune cell populations within the GBM microenvironment are tumor-associated macrophages (TAMs), immunosuppressive myeloid-derived suppressor cells (MDSCs), and CD4+CD25+Foxp3+T-regulatory cells (Tregs) that function as tumor growth promoters and induce T-cell dysfunction." (PMID 39267734, 2024). "It was reported that CD4 T cells and the prognosis of tumor patients were associated." (PMID 39256364, 2024). "Comparably, the Hot tumor cluster with the highest immune score and microenvironment score, exhibited positive association with T cell activation, evidenced by the highest degree of CD4+ T cells, CD4+ Tcm, CD8+ T cells, and CD8+ Tcm." (PMID 36991000, 2023). "In addition, we evaluated the prevalence of tumor-infiltrating FOXP3+ Tregs within CD4+ T cells and tumor-associated macrophages (TAMs) by flow cytometry." (PMID 37906252, 2023). "Furthermore, it was recently reported that CD4 + T cells in the tumor microenvironment are also associated with longer survival after the initiation of ICIs22." (PMID 37402763, 2023). "Furthermore, the beneficial effects of neoadjuvant chemotherapy were associated with infiltration of cytotoxic CD4 T cells into the tumor center." (PMID 37654482, 2023). "The results revealed that β3GNT9 expression was significantly and positively associated with the infiltration levels of CD4+T cells, macrophages, dendritic cells (P<0.05), but negatively correlated with tumor purity, B cells, CD8+T cells, and neutrophils (P<0.05)." (PMID 37771444, 2023). "Expression of MHC-II molecules was one of the key factors in the response to ICIs and may be associated with the recognition of tumor-specific antigens by helper CD4+ T cells during ICIs and the promotion of tumor inhibition." (PMID 36899891, 2023). "In addition, IDO-1 activity leads to the suppression of effector T and NK cells and the promotion of angiogenesis in solid tumors, while IDO-1 deficiency causes a stark depletion of Tregs and tumor rejection mediated by CD4+ and CD8+ T cells." (PMID 37046685, 2023). "The reduction of CD4+ T helper lymphocytes may cause a poor lymphocyte-mediated immune response to tumor cells." (PMID 37974129, 2023). "Studies have shown that CD73/adenosine signaling is associated with tumorigenesis and tumor progression through inhibition of CD4+T cells and NK cell proliferation, while augmenting suppressive immune subsets such as Tregs, regulatory B cells, and myeloid-derived suppressor cells." (PMID 37180168, 2023). "Both CD8+ and CD4+T cells can mount responses against many human cancer types, especially those with higher mutational burden and several studies in different tumour types have shown a correlation between tumor-infiltrating effector CD8+ T cells and favorable clinical outcomes." (PMID 37426665, 2023). "Tumor-associated B-cells’ role as negative regulator could be explained by their ability to act as antigen presenting cells inducing CD4+ T cells activation, differentiation, and polarization in Th1 and Th2 subtypes." (PMID 36776840, 2023).
tumor (continued). "Considering an eTreg-polarized CD4+ T-cell landscape in NPC, we hypothesized that increased intratumoral Treg abundance and suppressive activity might be collectively caused by tumor-mediated CD4+ naïve T cell-to-Treg development and Treg activation." (PMID 37024479, 2023). "Ongoing research explores the significance of MHC-II expression on tumor cells, current evidence indicates that it enables the direct presentation of tumor neoantigens to CD4+ T helper cells and is linked to improved outcomes in surgically removed lung adenocarcinomas." (PMID 37760516, 2023). "Coincidentally, it was demonstrated that the better prognosis in the early stage may be due to the better anti-tumor effect caused by the cellular immunity of CD4+ and CD8+ T lymphocytes." (PMID 37520979, 2023). "RGP induced DCs maturation and activated antigen-specific immune responses in tumor-bearing mice, causing significant increases in CD4+ and CD8+ T cells, increased mRNA levels of the transcription factor T-BET in Th1 cells, and promoted CSFE-labeled OT-I and OT-II T cells to infiltrate the tumor." (PMID 37876967, 2023). "Furthermore, CD4+ cells recognize tumor cells through the interaction of the T-cell receptor with the tumor antigen that is associated with the MHC-I complex on tumor cells in the presence of costimulatory molecules (CTLA4/CD4+ T cells–B7 tumor cells)." (PMID 37111629, 2023). "Interestingly, consequent to disease progression, the administration of >95% pure population of mutation-reactive Th1 type CD4+ cells further induced tumor regression in a patient." (PMID 38328405, 2023). "Meanwhile, RCQ suppressed the development of tumor-infiltrating lymphocytes into immunosuppressive cell subpopulations, including CD4+ T cells to T helper Type 2 type (Th2), tumor-associated neutrophils (TANs) to the N2 TANs, and tumor-associated macrophages (TAMs) cells to M2 TAMs." (PMID 37587146, 2023). "Similarly, higher CD4+T cell density at tumor margin is associated with better OS or DFS, and the distribution of CD8+T cells within and around the tumor also affects the prognosis of CCA patients." (PMID 37064120, 2023). "However, using RITs to deplete Tregs has strong side effects, as this treatment method affects CD4+CD25hi effector T cells, further weakening the body’s anti-tumor immunity and increasing the risk of the patient developing autoimmune diseases." (PMID 37753092, 2023). "Thus, a low CD4+ T-lymphocyte content is associated with worrying clinical features in the course of tumor development." (PMID 37206348, 2023). "Several preclinical studies have demonstrated that tumor-specific CD4+ T cells might recognize immunogenic mutations." (PMID 37638022, 2023). "Furthermore, we found that LUAD patients in the high‐risk group had higher infiltration of tumor‐infiltrating immune cells, such as M0 macrophages, neutrophils, resting mast cells, and activated memory CD4+ T cells, than patients in the low‐risk group." (PMID 36507553, 2023). "In addition, high levels of resting memory CD4+ T cells in ccRCC have been associated with improved outcomes because these cells can further differentiate into CD8+ T cells to suppress tumor growth." (PMID 37240841, 2023). "CDC27 is the first tumor-associated antigen identified that is well recognized by CD4+ TILS." (PMID 37112747, 2023). "In addition, the expression levels of inhibitory receptors on CD4+ T cells seem to be associated with tumor progression and clinical stage." (PMID 37829505, 2023). "Our analysis in the training and test cohorts revealed that low-risk subgroup had higher proportions of anti-tumor immune cells, including B cells, CD4+T cells, CD8+T cells, and M2 macrophages, however, the abundance of immune cell infiltration of neutrophil was upregulated in high-risk group." (PMID 37941546, 2023).